CD47 (CD47 molecule)
Diseases named in the same sentence as CD47 in open-access papers (continued):
Sharing a sentence is not in itself a finding about the gene and the disease.
breast carcinoma (continued). "In contrast, phosphorylation of PDK1 at Ser241, which induces a cancer stem cell gene expression signature, was negatively correlated with CD47 mRNA expression and was the fourth most significant change in protein phosphorylation in the breast cancer dataset (p = 0.0015)." (PMID 26840086, 2016). "Furthermore, CD47 expression was significantly higher in TNBC than in other breast cancers (p = 1.7×10−9)." (PMID 26840086, 2016). "Finally, studies in combination with clinical data have shown that overexpression of CD47 on circulating tumor cells correlates with dismal survival and increased metastasis in a small cohort of metastatic luminal breast cancer patients." (PMID 26674012, 2015). "In the previous cases (with and without treatments), we have considered that metastases in the bone are originated only by breast cancer cells with four driver mutations relative to four proteins EPCAM, CD44, CD47 and MET, and they correspond to four branching of the CTCs departing from the DLU." (PMID 25978366, 2015). "However, no large-scale study had examined the clinical impact of MET and CD47 co-expression in luminal-type breast cancer patients." (PMID 25230070, 2014). "In order to validate that MET-CD47 co-expression is linked to dismal outcome and metastasis in vivo, we first re-analyzed the previously generated flow cytometry (FACS) data of luminal-type metastatic breast cancer patient CTCs for the specific presence of double positive MET+CD47+ CTCs." (PMID 25230070, 2014). "We hypothesize that MET and CD47 co-expression provides complementary assets to luminal-type breast cancer cells during the metastatic process such as invasiveness, motility and escape from macrophage-mediated phagocytosis." (PMID 25230070, 2014). "Therefore, implementing anti-CD47 antibodies to anti-HER2 treatment of HER2+ breast cancer may be beneficial in treating those patients whose cancers have progressed after anti-HER2 therapy." (PMID 38892394, 2024). "Therefore, SIRPα-Fc may be a selective CD47-dependent inducer of stem cell character in these breast carcinoma cells." (PMID 38495618, 2024). "Thus, CD47 expression is fatal for breast cancer phenotype that is mediated by HIF-1α." (PMID 36014432, 2022). "Notably, the regulatory effect of MYC on CD47 in breast cancer requires further studies." (PMID 35860564, 2022). "In the third pathway, anti-CD47 antibody could eliminate breast cancer cells via traditional Fc-dependent mechanisms, including neutrophil-mediated antibody-dependent cellular cytotoxicity (ADCC) and macrophage-mediated antibody-dependent cellular phagocytosis (ADCP)." (PMID 35860564, 2022). "This study also suggests that tumors resided in a lipid-enriched microenvironment such as GBM and breast cancer brain metastasis, CD47-mediated immunosuppressive status could be readily adopted by the tumor cells via rewiring FA combustion with aggressive growth and immune evasion." (PMID 35314680, 2022). "Moreover, NF-κB signaling reportedly regulates CD47 expression in breast cancer cells." (PMID 34349643, 2021). "Indeed, metformin treatment could cause the restoration of miR-708 that is a cellular/tissue miR and decrease the expression level of CD47 which consequently results in chemo-sensitivity in breast cancer." (PMID 33849540, 2021). "The co-expression of CD44 and CD47 in tumor cells may contribute to breast cancer metastasis." (PMID 34205080, 2021). "The role of CD47 and PD-L1 expression on circulating tumor cells (CTCs) remains unclear, and it is currently unknown whether their distribution varies between the blood and tumor tissue in breast cancer (BC)." (PMID 32041353, 2020). "Furthermore, poor response to chemotherapy (e.g., trastuzumab in breast cancer patients) may correlate with tumor cell CD47 expression." (PMID 35582455, 2020).
breast carcinoma (continued). "In breast cancer, only a few studies focused on CD47 at the cytological level, such as breast cancer cell lines, breast cancer stem cells, peripheral blood cells and circulating tumor cells of breast cancer patients, the expression of CD47 in breast cancer solid tumors have been rarely reported." (PMID 31528120, 2019). "To further examine the relationship between UPR signaling and CD47, we used the KM-plot data base (kmplot.com) and mined the breast cancer dataset to assess whether co-expression of GRP78 and CD47 impact the relapse-free survival (RFS) of breast cancer patients." (PMID 28815041, 2017). "We found that particularly in breast cancer cells, CD47 expression is increased by an inflammatory pathway whereby the NFKB1 transcription factor directly regulates the expression of the gene by binding to a specific constituent enhancer within an active breast cancer SE (proposed mechanism)." (PMID 28378740, 2017). "Besides MICs in breast cancer, CD47 was strongly expressed on CTCs from colorectal cancer patients and might act as antagonist of innate immune cells during circulation." (PMID 27683128, 2017). "We characterized CD47 expression across key solid tumor indications being evaluated clinically using anti-CD47 blockade agents: HNSCC, breast cancer and CRC." (PMID 41415295, 2025). "We also tested the effect of VOR on CD47 expression in SW480 CRC cells, PANC-1 pancreatic cancer cells and MDA-MB-231 breast cancer cells." (PMID 39994810, 2025). "Nanoparticles coated with CD47-positive CCM show an extended circulatory stability and induce targeted cytotoxicity against breast cancer." (PMID 40072370, 2025). "This study highlights the prognostic importance of Trop-2, CD47, and CD163 expression in TNBC, an aggressive and treatment-resistant subtype of breast cancer." (PMID 39857116, 2025). "Blocking CD47 reverses this resistance, as demonstrated in HER2-positive breast cancer models where trastuzumab efficacy was restored." (PMID 40568594, 2025). "We found that treatment with the CD47 antibody B6H12 altered gene expression in CD47-expressing triple-negative MDA-MB-231 breast carcinoma cells, resulting in suppression of breast cancer stem cell (bCSC) characteristics." (PMID 38495618, 2024). "CD47 antibody treatment or CD47 knockdown suppressed stem cell character in hepatocarcinoma, MDA-MB-231 breast carcinoma, and glioma cells." (PMID 38495618, 2024). "CD47 is a glycoprotein widely expressed in tumor cells and is highly expressed in patients with various cancers, including HCC, breast cancer, glioblastoma, lung cancer, colorectal cancer, and ovarian cancer." (PMID 39664519, 2024). "Analysis of datasets derived from thousands of breast cancer patients unveiled the connection between the expression of HIF-1 (hypoxia-inducible factor), CD47, and increased mortality of patients." (PMID 38892394, 2024). "Some biomarkers, which have been mentioned here, and researched for their clinical utility in locating and characterizing breast cancer include EGFR, HER2, ER, CD24, CD44, and CD47." (PMID 40051976, 2024). "Silencing CD47 also downregulated MTT-based viability, whereas it significantly suppressed CALR-induced tumor inhibition in U2OS OS cells, TT2 OS cells, MDA-MB-231 breast cancer cells, and PANC1 pancreatic cells." (PMID 36943734, 2023). "We investigated the relationships between tumor expression of CD47 and CD68 macrophage content, subsets of tumor‐infiltrating lymphocytes (TILs), and vascular invasion in breast cancer." (PMID 36598153, 2023). "For melanoma, breast cancer, and NSCLC, blocking the CD47/SIRPα pathway is an effective treatment strategy." (PMID 37138855, 2023). "According to a study conducted by Betancur P. and colleagues, SEs significantly upregulate the CD47 enzyme, which is highly expressed in T-ALL and breast cancer cells." (PMID 37190100, 2023).
breast carcinoma (continued). "To determine the biological significance of Kaiso with the THBS1/CD47/SIRPA signaling axis, we first analyzed two datasets that contained gene expression from commonly utilized breast cancer cell lines." (PMID 37190208, 2023). "Depleted expression of Kaiso in breast cancer cells modulates the immune signaling molecules within the cargo of exosomes, resulting in increased THBS1 expression and decreased CD47 and SIRPA expression, as well as in decreased phagocytosis by macrophages." (PMID 37190208, 2023). "Collectively, our findings suggest that Kaiso, CD47, SIPRA, and THBS1, gene signature is related to ER-negative basal-like tumors, which includes TNBC breast cancer patients." (PMID 37190208, 2023). "Most importantly, UEs from breast cancer patients carry more abundant key proteins (CD63, CD9, and CD47) as compared to that from normal people, which are essential for long blood circulation, immune escape and tumor targeting." (PMID 36004889, 2022). "Intriguingly, GRP78 inactivation downregulated the expression of innate immune checkpoint CD47 in breast cancer cells, whereas reduction of GRP78 in normal mammary tissue increased the expression of CD47 and macrophage infiltration." (PMID 35127545, 2022). "Through the analysis of the public GEO database, the evaluated expression level of CD47 and PVR was also validated in esophageal squamous cell carcinoma, colon cancer, and breast cancer tissues in the GSE23400, GSE44076, and GSE42568, respectively." (PMID 34068552, 2021). "In response to TNFα, activated NFκB (nuclear factor- κB) directly binds to a specific constituent enhancer of CD47 and increases its gene expression in MCF-7 breast cancer cells resulting in tumor growth by inhibiting phagocytosis." (PMID 34512146, 2021). "Silencing of CD47 and SIRP-a promote breast cancer cells death by PMA-differentiated THP-1 cells, and radiation-induced loss of cell surface CD47 enhances immune-mediated clearance of human papillomavirus-positive cancer." (PMID 33867819, 2021). "CD47 and PVR were highly co-expressed on the human esophageal squamous cell lines KYSE-70 and EC9706, the colorectal cancer cell line HT29, and the breast cancer cell line MCF7." (PMID 34068552, 2021). "High expression of CD47, CD49c, CD44, and ALDH1A1 suggests the breast cancer origin of the KAIMRC2 cell line." (PMID 34073849, 2021). "In this study, the authors demonstrate that CD47 and HER2 are coordinating in tumor response to radiation and that co-blockage of both receptors can eliminate radiorestistant breast cancer cells." (PMID 32929084, 2020). "In this sense, it has been observed that treating human or murine TNBC cells with chemotherapeutics, induces a coordinate transcriptional program of CD47, CD73, and PD-L1, leading to higher percentage of CD47+CD73+PDL1+ breast cancer cells." (PMID 33184339, 2020). "Remarkably, CD24 is a direct target of Wnt1 in breast cancer, while CD47 is an indirect target of Wnt signaling mediated by SNAI1 and ZEB1 in breast cancer." (PMID 33234169, 2020). "Several studies have reported that exosome biomarkers (such as CD44, CD47, CXCR4, Del-1, HER2, and KDR) can be used for early diagnosis and prognosis of breast cancer patients." (PMID 32826923, 2020). "We also found that MYC expression correlates with CD47 expression in human whole breast tumor tissue, circulating monocytes, and tumor-associated monocytes in patients with breast cancer, indicating that MYC regulation of CD47 may be conserved within breast cancer TAMs as well." (PMID 32685002, 2020). "However, the exact role of CD47 in the prognosis of breast cancer remains unclear." (PMID 31528120, 2019). "In this study, we evaluated the expression and prognostic significance of CD47 and CD68-labeled TAMs in breast cancer solid tumors." (PMID 31528120, 2019).
breast carcinoma (continued). "The MYC pathway, PD-L1 (CD274) and CD47 were elevated in TNBC, particularly in PTEN-low/miRNA-low TNBCs (group “a”), relative to HER2+ or ER+ breast cancer in most cohorts." (PMID 31836816, 2019). "Secondly, the prognostic significance of CD47 and CD68 in breast cancer was discussed only at histological level." (PMID 31528120, 2019). "Disrupting CD47/SIRPα signaling transduction by blocking antibodies (Hu5F9-G4 and CC-90002) could increase macrophage phagocytosis of multiple tumor cells and has been proved as a promising immunotherapeutic method for melanoma, breast cancer, small cell lung cancer and acute myeloid leukemia." (PMID 31829270, 2019). "The expressions of MYC and its downstream immune checkpoint genes (CD47 and PD-L1) in samples with TNBC and Her-2 positive breast cancer were detected by qRT-PCR." (PMID 29416769, 2018). "Moreover, the blockade of tumor necrosis factor (TNF)-α reduced CD47 and increased phagocytosis, suggesting that the TNF-NF-κB signaling pathway directly governs CD47, by interacting with a constituent enhancer placed within a CD47-associated SE specific to breast cancer." (PMID 30213113, 2018). "Notice how all the breast cancer cell lines show significant binding with our CD47 labeled SERS NPs, apart from our negatively expressing CD47 cell line, DLD−." (PMID 30463284, 2018). "We found a statistically significant decrease (p = 0.02) in survival in all subtypes of breast cancer in over 1700 patients when both GRP78 and CD47 were co-expressed." (PMID 28815041, 2017). "First, E5, in the downstream CD47 SE seen in breast cancers, showed increased reporter activity specifically in the MCF7 breast cancer cell line." (PMID 28378740, 2017). "An analysis of circulating tumor cells isolated from the blood of patients with breast cancer revealed a population of metastasis-initiating cells (MICs) that express EPCAM, CD44, CD47 and MET." (PMID 27706047, 2016). "A number of the identified CD47-dependent genes including MBP1, TBL1XR1, girdin, cyclin D1, CDC27, SPAG9, and JAK1 have reported functions in breast cancer progression." (PMID 26840086, 2016). "Consistent with the diminished sensitivity of ER+ breast cancer cells to B6H12 observed in vitro, CD47 mRNA expression in the TCGA dataset was negatively correlated with ER and with HER2 protein expression (p = 1.7×10−6 and 2.5×10−5, respectively)." (PMID 26840086, 2016). "In 2013, Baccelli studied metastasis of circulating tumor cells in the blood of breast cancer patients and reported that metastasis-initiating cells had an EPCAM+CD44+CD47+c-met+ phenotype." (PMID 25658794, 2015). "The expression of respective proteins (Trop2, CD49f, c-Met, CK8, CD44, ADAM8, CD146, TEM8, CD47) was verified by immunofluorescence on EpCAMpos (e.g. MCF7, SKBR3) and EpCAMlow/neg (MDA-MB-231) breast cancer cell lines." (PMID 26695635, 2015). "In 2013, Baccelli studied the metastasis of circulating tumor cells in the blood of breast cancer patients and reported that metastasis-initiating cells had an EPCAM+CD44+CD47+c-met+ phenotype." (PMID 25658794, 2015). "To systematically identify genetic regulators of CD47 surface expression, we performed FACS-based genome-wide CRISPR screens in three murine cancer cell lines B16 (melanoma), MC38 (colon adenocarcinoma), and EMT6 (breast carcinoma)." (PMID 41601654, 2026). "In 4T1 murine breast cancer models, Ir1-PDT achieves potent tumor suppression and transforms immunologically "cold" tumors into "hot" lesions through the synergistic interplay of ICD and CD47 pathway disruption." (PMID 41298247, 2025). "Developmental endothelial locus-1 (Del-1) levels in blood EVs were higher in early-stage breast cancer patients than in those with non-cancerous breast diseases, while the CD47 level was lower than that of healthy controls." (PMID 39062561, 2024).
breast carcinoma (continued). "Therefore an integrated therapeutic approach targeting blockade of both CD47 and HER2 is needed in order possibly to abolish resistant cancer cells in radiotherapy of breast cancer." (PMID 38892394, 2024). "CD47 regulates cell death across various cell types, including B-cell chronic lymphocytic leukemia (B-CLL), T cell acute lymphoblastic leukemia (T-ALL), and breast cancer cells, as well as certain healthy cell lineages." (PMID 39039207, 2024). "However, the relationship between CD47 and other microenvironment features such as TIL subtypes, and how these factors promote early tumor spread by blood vessel invasion in breast cancer tissues are less investigated." (PMID 36598153, 2023). "Also, in several preclinical studies, researchers have investigated potential therapeutic approaches combining anti-CD47 strategies with anti-CD20 strategies for lymphoma, anti-HER2 strategies for breast cancer, and anti-EGFR strategies for colorectal cancer." (PMID 38033495, 2023). "These experimental observations may support our findings that CD47 and CD68 combined are strongly related to both lymphatic and blood vessel invasion in breast cancer." (PMID 36598153, 2023). "Recently, it has been demonstrated that administration of anti-CD47 antibodies significantly enhanced trastuzumab-mediated ADCP and improved antitumor responses and may help to resensitize refractory HER2+ breast cancers to trastuzumab treatment." (PMID 37046648, 2023). "Excised xenografts were assessed histologically by H&E staining and immunohistochemistry for breast cancer marker (ERB1), proliferation marker (Ki67), mitotic marker (pHH3), hypoxia marker (HIF-2α), CSC markers (CD47, CD44, CD24, and CD133), and vascularization markers (CD31, CD34)." (PMID 34205080, 2021). "Also in breast cancer, JQ1 has been reported to decrease the expression of CD47, through disruption of the super enhancers that regulate CD47 expression." (PMID 33859645, 2021). "CD47 overexpression has been reported to enhance the CD44+/CD24− population in breast cancer, but not sufficiently to increase its stemness." (PMID 34205080, 2021). "In addition to the combination of anti-CD47 with regular chemotherapy, it can also be used with biologics, such as combining CD47 blockade with trastuzumab, which eliminates HER2-positive breast cancer cells and overcomes trastuzumab tolerance." (PMID 34717705, 2021). "Therapies against CD47 are also being applied in several clinical trials, although not specifically in breast cancer." (PMID 32974189, 2020). "In summary, combined high expression of CD47 and CD68 is associated with the prognosis of breast cancer, especially for hormone receptor-negative breast cancer." (PMID 31528120, 2019). "Therefore, exploring the relationship between CD47/CD68 protein and proliferation/growth factor is also essential to better demonstrate the role of CD47 and CD68 in the prognosis of breast cancer." (PMID 31528120, 2019). "In addition, combined high expression of CD47 and CD68 (CD47highCD68high) were found in 49.8% of breast cancer patients (108/217)." (PMID 31528120, 2019). "Our study showed for the first time that CD47highCD68high represented an even better independent predictor for poor prognosis compared to the expression of CD47 or CD68 alone in breast cancer patients, especially in patients lacking of hormone receptor." (PMID 31528120, 2019). "FACS revealed consistent binding of our SERS-CD47 NPs to each of the breast cancer cell lines as opposed to the negatively CD47 expressing cell line DLD−." (PMID 30463284, 2018). "Our results suggest that Raman imaging of our CD47 targeting SERS nanoparticles could play a significant role in identifying and localizing residual breast cancer to help guide surgeons in the OR." (PMID 30463284, 2018).